VPS35 (VPS35 retromer complex component)
Diseases named in the same sentence as VPS35 in open-access papers (continued):
Sharing a sentence is not in itself a finding about the gene and the disease.
retinal degeneration (2 papers, 2016 to 2020). Degeneration of the retina. "Consequently, loss of either Vps35 or Vps26 leads to aberrant Rh1 trafficking, resulting in lysosomal stress and progressive retinal degeneration." (PMID 32286230, 2020). "However, in dPLD3.1 photoreceptors, overexpression of vps35 results in two key outcomes: (i) the increased numbers of RLVs seen in dPLD3.1 are reduced back to wild type levels and (ii) the retinal degeneration of dPLD3.1 is suppressed." (PMID 27848911, 2016). "We tested the effect of overexpressing vps35 in photoreceptors during illumination; in an otherwise wild-type fly, this did not result in changes in RLV number or caused retinal degeneration." (PMID 27848911, 2016). "Interestingly, in the Drosophila visual system, we found that raising Vps29 or Vps35 mutants in the dark rescued retinal degeneration but not synaptic transmission defects, consistent with an uncoupling of retromer requirements in these two spatially distinct processes." (PMID 32286230, 2020).
synucleinopathy (2 papers, 2014 to 2019). A neurodegenerative disease that is characterized by the abnormal accumulation of aggregates of alpha-synuclein protein in neurons, nerve fibers or glial cells. "At 12 weeks postinjection, we do not observe alterations in the distribution of total or phosphorylated (Ser129) α-synuclein, a major component of Lewy body pathology in PD and other α-synucleinopathies, following human VPS35 expression." (PMID 24740878, 2014).
adrenocortical carcinoma (1 paper, 2026). "Analysis of VPS35 mutation frequency across pan-cancer revealed that uterine corpus endometrial carcinoma (5.7%), adrenocortical carcinoma (4.3%), and skin cutaneous melanoma (4.2%) exhibited the highest mutation rates, with structural variants (SV) being the most common mutation type of VPS35." (PMID 41531939, 2026).
behavior disorders (1 paper, 2021). "Additionally, in mouse models, a lack of VPS35 or pathogenic VPS35 mutations can lead to the accumulation and aggregation of α‐synuclein, accompanied by DA neuronal degeneration, decreased DA levels, motor behavior disorders, and lysosomal morphological changes." (PMID 37786555, 2021).
Brain atrophy (1 paper, 2020). Partial or complete wasting (loss) of brain tissue that was once present. "Loss of Vps35 in embryonic neurons results in not only terminal differentiation deficits, but also neurodegenerative pathology, such as cortical brain atrophy and reactive glial responses." (PMID 31907392, 2020).
brain tumor (1 paper, 2018). "Expression of the Vps35 transgene in type II neuroblast lineages, by PntP1-Gal4, fully suppressed the brain tumor phenotype caused by vps35 mutation." (PMID 30176986, 2018). "Taken together, our results clearly indicate that the brain tumor phenotype in vps35 mutants is caused by cell fate reversion of Dpn- Ase- neural progenitors." (PMID 30176986, 2018). "Whereas simultaneous overexpression of Nedd4 and Ndfip barely exhibited any effect on brain tumor phenotype caused by vps35 mutation, coexpression of Su(dx) and Ndfip indeed led to a complete rescue of the supernumerary neuroblast phenotype in vps35 mutants." (PMID 30176986, 2018). "Therefore, the reverting Dpn-Ase- neural progenitors are the cellular origin of brain tumor in vps35 mutants." (PMID 30176986, 2018). "Importantly, mammalian Vps35 physically interacts with Notch, colocalizes with Notch in neural progenitors, and its neuroblast-lineage-specific expression fully rescues neural progenitor-derived brain tumor phenotype in vps35 mutants." (PMID 30176986, 2018). "Importantly, human Vps35 also fully rescued the brain tumor phenotype of vps35 mutants back to wild type." (PMID 30176986, 2018). "(A,B) Neuroblast-specific coexpression of both Su(dx) and Ndfip but not either alone potently inhibited brain tumor phenotype in vps35 mutants." (PMID 30176986, 2018).
cognitive deficits (1 paper, 2024). "VPS35 deficiency was also found to severely impede Aβ endocytosis by DAM and exacerbate cognitive deficits in 5xFAD mice." (PMID 38831312, 2024).
corneal dystrophies (1 paper, 2017). "Intriguingly, cell surface targeting of SLC4A11, a membrane transport protein (OH- /H+ /NH3 /H2O) of corneal endothelium, whose mutations have been identified in patients with corneal dystrophy, was impaired in Vps35-deficient cells and cornea." (PMID 28934248, 2017). "In this model, corneal endothelial Vps35 is necessary for SLC4A11’s endosome-to-Golgi trafficking, and thus promoting SLC4A11’s cell surface targeting and protein stability, which may underlie Vps35’s involvement in the pathogenesis of corneal dystrophy." (PMID 28934248, 2017). "In this paper, we provide evidence for loss of Vps35 in mouse cornea causes corneal dystrophy." (PMID 28934248, 2017). "However, it remains to be determined if Vps35 mutation or deficiency occurs in corneal dystrophy patients, and if expression of SLC4A11 could attenuate corneal dystrophy in Vps35 mutant mice." (PMID 28934248, 2017). "As the deficit similar to the pathology of corneal dystrophy, we speculate that Vps35/retromer, via its various cargos in cornea, plays an important role in suppressing corneal stroma edema and promoting cell proliferation." (PMID 28934248, 2017). "These morphological alterations (e.g., enlarged cell size, disorganized cell distribution, altered cell density, increased thick-ness, and excrescences in the endothelial membrane) in Vps35+/- cornea resembled in certain degree to that of corneal dystrophy-like deficit." (PMID 28934248, 2017). "Here we provide evidence for a critical role of Vps35 in mouse corneal dystrophy." (PMID 28934248, 2017). "Nevertheless, our study does not exclude the possibility that other cargo proteins may be negatively impacted by Vps35 haploinsufficiency and involved in the pathogenesis of corneal dystrophy." (PMID 28934248, 2017). "Taken together, these results suggest that SLC4A11 appears to be a Vps35/retromer cargo, and Vps35-regulation of SLC4A11 trafficking may underlie Vps35/retromer regulation of corneal dystrophy." (PMID 28934248, 2017).
cyst (1 paper, 2016). A sac-like closed membranous structure that may be empty or contain fluid or amorphous material. "As the WT cyst matured, EEA1/Vps35-labelled EE and Rab11a-labelled RE became spatially resolved in the apical cytoplasm." (PMID 26786190, 2016).
diabetes (1 paper, 2022). "Our study elucidated that HG induced Golgi stress was mediated by NLRP3/Vps35/Golph3/Vimentin pathway, inhibition of NLRP3 and Golph3 by selected molecular inhibitors zafirlukast and bromocriptine could suppress neuro-inflammation and Golgi stress thus ameliorate diabetes cognitive decline." (PMID 36378718, 2022).
dilated cardiomyopathy (1 paper, 2024). Cardiomyopathy which is characterized by dilation and contractile dysfunction of the left and right ventricles. "VPS35 was mainly enriched in BPs, such as regulation of glycoprotein metabolic processes and poly a plus mRNA export from the nucleus, and KEGG pathways, such as dilated cardiomyopathy and RNA degradation." (PMID 38528539, 2024).
eye degenerative disorder (1 paper, 2017). A neurodegenerative disease that involves the eye. "However, Vps35/retromer’s function in the eye or the contribution of Vps35-deficiency to eye degenerative disorders remains to be explored." (PMID 28934248, 2017).
Fibroadenoma (1 paper, 2021). A benign tumor of the breast characterized by the presence of stromal and epithelial elements. "In women with fibroadenoma, an autoantibody response occurred against VPS35 (p = 0.007 compared to control women), SERBP1 (p < 0.0001 compared to control women), KRT8 (p = 0.03 compared to control women), and PDIA6 (p = 0.003 compared to control women)." (PMID 33976232, 2021).
gallbladder cancer (1 paper, 2026). "Additionally, VPS35 exhibited broad-spectrum expression across pan-cancer cell lines, with particularly high levels in gallbladder cancer and leukemia." (PMID 41531939, 2026).
glioma (1 paper, 2020). A benign or malignant brain and spinal cord tumor that arises from glial cells (astrocytes, oligodendrocytes, ependymal cells). "In the same work, the authors showed that GOLPH3 is physically associated with both Vps35 and Wls in the U251 glioma cell line and that GOLPH3 regulates Wls at the protein, but not at the transcriptional, level." (PMID 32023813, 2020). "As said above, GOLPH3 interacts with the VPS35 retromer protein and Wnt/β-catenin, and consequently, Wntless (Wls, the chaperone protein of Wnt secretion) are important in glioma etiology." (PMID 32023813, 2020).
Hepatitis (1 paper, 2026). Inflammation of the liver. "The inability to obtain patients' detailed history of co-morbidities (e.g., hepatitis viral loads, hepatic function indexes), which may affect the expression of VPS35." (PMID 41531939, 2026).
HIV-1 infection (1 paper, 2014). The type species of lentivirus and the etiologic agent of acquired immunodeficiency syndrome (AIDS). "Furthermore, western blotting of cell lysates showed that HIV-1 infected cells (>95% of cells HIV-1 Gag+) and uninfected cells expressed similar levels of Vps26 and Vps35 protein, demonstrating that HIV-1 infection alone does not modulate retromer expression." (PMID 25393110, 2014).
Huntington disease (1 paper, 2022). Huntington disease (HD) is a rare neurodegenerative disorder of the central nervous system characterized by unwanted choreatic movements, behavioral and psychiatric disturbances and dementia. "The retromer has also been implicated in Huntington’s disease (HD), as SorCS2, which is downregulated in R6/2 and zQ175 HD mouse models, which in turn downregulates VPS35." (PMID 34370162, 2022).
ischemia (1 paper, 2019). A hypoperfusion of the BLOOD through an organ or tissue caused by a PATHOLOGIC CONSTRICTION or obstruction of its BLOOD VESSELS, or an absence of BLOOD CIRCULATION. "Together, these results suggest an attenuation of ischemia/stroke-induced cortical brain injury in microglial VPS35-deficient mice." (PMID 31771656, 2019). "In summary, we have found a protective effect on ischemia/stroke-induced cortical brain injury by microglial VPS35 deficiency." (PMID 31771656, 2019). "To access microglial VPS35’s function in ischemia/stroke, we took advantage of the microglial VPS35 cKO mice and examined their response to photothrombotic cortical stroke injury." (PMID 31771656, 2019).
lateral sclerosis of (1 paper, 2024). "VPS35 is also involved in various neurodegenerative diseases, such as Parkinson’s disease (PD) and lateral sclerosis of the spinal cord." (PMID 38831312, 2024).
lung adenocarcinoma (1 paper, 2026). A carcinoma that arises from the lung and is characterized by the presence of malignant glandular epithelial cells. "These images demonstrated elevated VPS35 expression in COAD, LIHC, LUAD (lung adenocarcinoma), and PRAD (prostate adenocarcinoma) tissues compared to normal controls." (PMID 41531939, 2026).
lymph node metastasis (1 paper, 2021). "Our prediction results also showed that the significant correlations of VPS35 with lymph node metastasis, ER/PR negative status, HER2 positive status and triple negative molecular subtype." (PMID 34001111, 2021).
mandibulofacial dysostosis (1 paper, 2014). A hereditary disorder occurring in two forms: the complete form (Franceschetti's syndrome) is characterized by antimongoloid slant of the palpebral fissures, coloboma of the lower lid, micrognathia and hypoplasia of the zygomatic arches, and microtia. "Interestingly, the first gene, VPS35 (ENSG00000069329), is associated with “Parkinson's disease (PD)”, and the second gene, EFTUD2 (ENSG00000108883), causes “mandibulofacial dysostosis with microcephaly”." (PMID 24800246, 2014).
Parkinson’s disease 17 (1 paper, 2020). "On the other hand, VPS35 is one of the PD-linked products (also known as Parkinson’s disease 17 - PARK17) and the third autosomal-dominant gene associated with PD." (PMID 32266064, 2020).
proteinopathies (1 paper, 2026). "In aggregate, these findings provide evidence that TDP-43 dysfunction modulates the APA of retromer component VPS35, reducing the expression of VPS35 and VPS29, thereby uncovering a potential mechanistic link between TDP-43 loss of function, APA, and retromer dysfunction in TDP-43 proteinopathies." (PMID 41490046, 2026).
Stroke (1 paper, 2019). Sudden impairment of blood flow to a part of the brain due to occlusion or rupture of an artery to the brain. "Together, our results suggest associations of the reduced stroke injury in VPS35 mutant brain with decreases in iNOS+ microglia and pro-inflammatory cytokines’ expression, and an increase in CD206+ microglial activation." (PMID 31771656, 2019). "To understand how microglial VPS35 deficiency results in a reduced cortical ischemia/stroke injury response, we examined microglial response to the stroke." (PMID 31771656, 2019). "While VPS35 deficiency contributes to the pathogenesis of neurodegenerative disorders, its function in stroke remains largely unclear." (PMID 31771656, 2019). "Finally, stroke-induced CX3CR1 protein levels are abolished in microglial VPS35-deficient mice." (PMID 31771656, 2019). "Further investigations are necessary to test the view if CX3CR1 acts as a cargo of VPS35 in microglial cells to participate in stroke-induced injury response." (PMID 31771656, 2019). "The reduction in stroke-induced CX3CR1 protein levels in VPS35 cKO brain suggests a role of microglial VPS35 in stabilizing CX3CR1 proteins in response to stroke." (PMID 31771656, 2019). "In microglial VPS35 KO mice, the injury response to photothrombotic stroke is reduced, which include decreased infarct area, attenuated neuronal death and reactive astrogliosis, and better sensorimotor regulated behavior functions." (PMID 31771656, 2019). "We found a decrease in LPL+ DAM, but an increase in CD206+ microglia (anti-inflammatory-like), in VPS35 mutant cortex after stroke." (PMID 31771656, 2019). "It is noteworthy that in contrast from stroke injury, CX3CR1 deficiency in AD animal models enhances Aβand Aβassociated brain pathology; and such enhanced Aβphenotypes are also observed in VPS35-deficient mice." (PMID 31771656, 2019). "Taken together, these results suggest that microglial VPS35 is likely to be necessary for stroke-induced DAM and pro-inflammatory microglial activation, and both type of microglia might be “neurotoxic” in the condition of stroke induced injury." (PMID 31771656, 2019). "In addition to the reduced infarct area in response to the ischemic injury, both VPS35 and CX3CR1 mutant mice show increased anti-inflammatory, but not pro-inflammatory, microglial activation by stroke and reduced stroke-induced expressions of pro-inflammatory cytokines." (PMID 31771656, 2019).
X-linked Parkinson’s disease (1 paper, 2023). "Rab39b, which has been reported to regulate alpha-synuclein accumulation and has loss-of-function mutations in X-linked Parkinson’s disease, was strongly depleted in VPS35 KO lysosomes." (PMID 37248224, 2023).
neurodegenerative disease (26 papers, 2015 to 2025). A disorder of the central nervous system characterized by gradual and progressive loss of neural tissue and neurologic function. "VPS35 is a critical component of the retromer cargo-selective complex and is implicated in neurodegenerative disease in patients with LRRK2 mutation." (PMID 40282191, 2025). "The retromer complex and its components, including VPS35, have been implicated in several neurodegenerative diseases." (PMID 40082954, 2025). "The VPS35 subunit, a key cargo-recognition component of the retromer, has been implicated in neurodegenerative diseases, with mutations such as L625P linked to early-onset AD." (PMID 40931359, 2025). "Deficiency of Vps35 has been reported as an active player in the pathogenesis of neurodegenerative disease." (PMID 35884959, 2022). "Dysfunctional Vps35/retromer is believed to be a risk factor for development of various neurodegenerative diseases." (PMID 34445101, 2021). "This is important for understanding the selective vulnerability of different neuronal populations to VPS35 deficiency that will provide key insight into neuronal susceptibility in different neurodegenerative diseases." (PMID 34704029, 2021). "Although numerous studies have demonstrated that Vps35 is an active player and directly involved in development of neurodegenerative diseases, the underlying mechanisms remain largely unclear." (PMID 34445101, 2021). "Several lines of evidence suggest that loss of the Vps35 function contributes to the development of neurodegenerative diseases." (PMID 34445101, 2021). "Vps35 dysfunction is considered to be a risk factor for neurodegenerative diseases, including AD and PD." (PMID 31907392, 2020). "While aberrant endosomal protein sorting has been linked to several neurodegenerative diseases, the mechanisms by which VPS35 mutations and retromer function contribute to PD pathogenesis are not clear." (PMID 26251041, 2015). "Importantly, the retromer has also been implicated in the pathological mechanisms of neurodegenerative diseases other than PD: e.g., VPS35 and VPS26 were reduced at both the mRNA and protein levels in the entorhinal cortex of patients with AD." (PMID 38886344, 2024). "Vps35 dysfunction is known to be a risk factor for the development of neurodegenerative diseases." (PMID 35884959, 2022). "Dysfunctional Vps35/retromer is a risk factor for the development of neurodegenerative diseases." (PMID 35884959, 2022). "Therefore, VPS35 is commonly implicated in many neurodegenerative diseases." (PMID 34704029, 2021). "Although alterations in other retromer components, such as VPS35 and VPS29, have been associated with cancer and neurodegenerative diseases, the role of VPS26A in malignancies, particularly LIHC, has not been thoroughly examined." (PMID 40731912, 2025). "Intriguingly, reduced protein levels of VPS35 have also been found in the entorhinal cortex of AD patients, leading to an increased focus on the role played by VPS35 in the pathophysiology of neurodegenerative diseases." (PMID 38409392, 2024). "VPS35 is a key subunit of the retromer complex responsible for recognising cytosolic retrieval signals in cargo and is involved in neurodegenerative disease and tumour progression." (PMID 37950040, 2024). "Our data reveal that VPS35 is critical for the normal maintenance and survival of motor neurons during post-natal development that has implications for neurodegenerative diseases, particularly ALS and related disorders." (PMID 34704029, 2021). "Emerging data indicate that VPS35 and the retromer play important roles in distinct neurodegenerative diseases." (PMID 34704029, 2021). "Vps35/retromer dysfunction is involved in pathogenesis of multiple neurodegenerative diseases, including AD and PD, FTD, and ALS." (PMID 34445101, 2021).